UBE2O (ubiquitin conjugating enzyme E2 O)
Diseases named in the same sentence as UBE2O in open-access papers (continued):
Sharing a sentence is not in itself a finding about the gene and the disease.
prostate carcinoma (9 papers, 2021 to 2025). A carcinoma that arises from epithelial cells of the prostate gland. "UBE2O is often intensified or mutated in many cancers, and its high expression is correlated with low survival rates of breast, gastric, lung, and prostate cancers." (PMID 34451875, 2021). "In mouse models of breast and prostate cancers, decreased tumor growth and metastasis rates were observed when one or both UBE2O alleles were lost." (PMID 34451875, 2021). "The rates of distant metastasis of UBE2O-deficient mice were much lower than those of UBE2O-proficient mice of prostate cancers." (PMID 34451875, 2021). "In mouse models of breast and prostate cancers, deferred tumor initiation and reduced tumor growth and metastasis rates were found to be attributable to the loss of one or both UBE2O alleles." (PMID 34451875, 2021). "This justify both genes UBE2T and UBE2O, and their respective protein expressions, being associated with several cancers and diseases, such as hepatocellular carcinoma, multiple myeloma (MM), bladder, gastric cancer, multiple myeloma, breast and prostate cancer, and mixed-lineage leukemia." (PMID 37373211, 2023). "Notably, UBE2O is often amplified or mutated in multiple cancers, and its high expression is associated with a low survival rate in patients with gastric, lung, breast, and prostate cancer." (PMID 37373211, 2023). "In prostate cancer, UBE2O expression is upregulated, negatively correlated with AMPKα2, and positively correlated with mTOR/HIF1α." (PMID 40426910, 2025). "In breast and prostate cancers, UBE2O promotes tumor cell proliferation and EMT by degrading AMPKα2 and activating the mTORC1 signaling pathway." (PMID 40426910, 2025). "In recent years, much attention has been paid to evaluating the role of UBE2O overexpression in the pathogenesis and progression of breast and prostate cancers." (PMID 39272922, 2024). "A positive correlation was reported between the expression of histopathological UBE2O staining and prostate cancer advancement." (PMID 36185617, 2022). "Kaplan–Meier survival analysis was performed and subsequently the log-rank test for UBE2O expression in patients with prostate cancer was run for the purposes of comparison." (PMID 34451875, 2021). "It was shown that ubiquitin conjugating enzyme E2T (UBE2T) exhibits oncogenic properties while genetic ablation of Ube2o (ubiquitin conjugating enzyme E2O) impairs progression of prostate cancer." (PMID 33572160, 2021). "The classifications for the 355 prostate cancer patients’ expression of UBE2O were as follows: grade 0 (n = 0), grade 1 (n = 120), grade 2 (n = 154), and grade 3 (n = 81)." (PMID 34451875, 2021). "For prostate cancer, there is a positive correlation between the expression of UBE2O staining and high PSA, pathological stage, and lymph node involvement." (PMID 34451875, 2021). "With prostate cancer, lymphatic metastasis can be anticipated with the expression of UBE2O immunohistochemical staining." (PMID 34451875, 2021). "Cox’s proportional hazard modelling for UBE2O expression also identified that UBE2O immunohistochemical staining correlated with clinical recurrence free survival (p < 0.001) and overall survival (p < 0.05) in prostate cancers." (PMID 34451875, 2021). "The purpose of this study is to examine the relationships between the expression of immunohistochemical UBE2O staining and the progression factors in prostate cancer patients." (PMID 34451875, 2021). "Obstructing UBE2O treatment resulted in decreased prostate lobe enlargement and high G-PIN prostate cancer development in TRAMP in UBE2O positive mice." (PMID 34451875, 2021). "In their result, it has been shown that high expression of UBE2O promotes tumor initiation in mouse models of prostate cancers." (PMID 34451875, 2021). "However, in breast and prostate cancer, upregulation of UBE2O induces the proliferation of cancer cells, promoting the ubiquitination and degradation of AMPKα2." (PMID 37373211, 2023).
prostate carcinoma (continued). "Similarly, knockout of UBE2O in TRAMP mice improves prostate cancer survival, invasion and metastasis." (PMID 37533513, 2022). "As mentioned, of the total 382 study population, the UBE2O immunohistochemical staining of prostate cancer could be assessed in 200 patients." (PMID 34451875, 2021). "UBE2O in prostatic cancer primarily materialized in the cytoplasm of tumor cells." (PMID 34451875, 2021). "The expression of UBE2O immunohistochemical staining facilitates prostate cancer prognosis." (PMID 34451875, 2021). "UBE2O plays a key role in the initiation, progression, invasion, and metastasis of prostate cancer." (PMID 34451875, 2021). "Hence, it can be concluded that the expression of UBE2O staining can facilitate the assessment of a prediction for prostate cancer prognosis." (PMID 34451875, 2021). "Thus, a prostate cancer prognosis can be assessed with the expression of UBE2O staining." (PMID 34451875, 2021). "The test of UBE2O inhibitor ATO in mouse models of breast and prostate cancers demonstrated that it can reduce tumor incidence and progression, and extend mouse survival." (PMID 37533513, 2022). "Hence, the expression of UBE2O immunohistochemical staining, PSA, Gleason score, and pathological stage can all predict prostate cancer prognosis." (PMID 34451875, 2021). "Although we have explored pilot UBE20 expression using human TMA prostate cancer tissue, UBE2O/antibody used validated antibody from Sigma-Aldrich but could not detect UBE2O expression in any of the 494 prostate cancer tissues." (PMID 34451875, 2021).
leukemia (6 papers, 2018 to 2025). A malignant (clonal) hematologic disorder, involving hematopoietic stem cells and characterized by the presence of primitive or atypical myeloid or lymphoid cells in the bone marrow and the blood. "The interleukin-1 (IL-1) signaling pathway, which is frequently hyperactivated in leukemia, potentiates UBE2O function via interleukin-1 receptor-associated kinase 4 (IRAK4)." (PMID 40426910, 2025). "UBE2O exhibits pro-oncogenic activity in solid tumors and leukemia, while functioning as a tumor suppressor in multiple myeloma (MM)." (PMID 40426910, 2025). "We further discuss UBE2O’s implications in various human diseases, particularly in leukemias and solid cancers." (PMID 39272922, 2024). "The review also explores UBE2O’s involvement in several human cancers, with a particular focus on its role in leukemias and solid cancers." (PMID 39272922, 2024). "In conclusion, UBE2O acts as an oncogenic factor in leukemia, but as a tumor suppressor in myeloma." (PMID 40426910, 2025). "Contrary to the hematological malignancies evaluated so far, for which the upregulation of UBE2O could represent a novel therapeutic strategy, other types of leukemia would benefit from the inhibition of UBE2O." (PMID 39272922, 2024). "Furthermore, this review addresses the implications of the altered expression of UBE2O in various human leukemias and solid cancers and highlights UBE2O potentialities as a target in several therapeutic strategies." (PMID 39272922, 2024). "Inhibition of IRAK4 to regulate UBE2O markedly increases the chromatin occupation of wild-type and inhibits the proliferation of MLL leukemia, which provides us a paradigm to develop a novel therapy method for aggressive MLL leukemia and other cancers caused by improper translocation." (PMID 37533513, 2022). "For instance, UBE2O has been found to control the stability of MLL/COMPASS and play an oncogenic role in MLL-rearranged leukemia." (PMID 32901121, 2021). "It has been reported that UBE2O could decrease the stability of MLL in a polyubiquitination-dependent manner, which results in aggressive leukemia." (PMID 34976998, 2021). "UBE2O has also recently been shown to induce the degradation of the mixed-lineage leukemia (MLL) protein, which is commonly fused to members of the P-TEFb-based super elongation complex in leukemia." (PMID 29845934, 2018). "In fact, overexpression of the MLL N-terminus of MLL, which cannot bind UBE2O but contains chromatin-binding domains, reduced the proliferation of SEM cells, indicating that destabilizing wild-type MLL is prerequisite for the proliferation of MLL leukemia cells." (PMID 37533513, 2022).
multiple myeloma (6 papers, 2017 to 2025). "Furthermore, the human MM xenograft in nude mice showed that re-expression of UBE2O delayed the growth of myeloma xenografts in nude mice in association with c-Maf downregulation and activation of the apoptotic pathway." (PMID 28673317, 2017). "Conversely, in multiple myeloma, UBE2O suppresses cell proliferation and survival by mediating the degradation of the transcription factor c-Maf, a key driver of the disease." (PMID 40426910, 2025). "For example, in multiple myeloma (MM), UBE2O can lead c-Maf (a transcription factor expressed in MM) to degradation, inhibiting cell growth mediated by apoptosis and acting as a tumor suppressor." (PMID 37373211, 2023). "UBE2O mediates c-Maf polyubiquitination and degradation, induces MM cell apoptosis, and suppresses myeloma tumor growth, which provides a novel insight in understanding myelomagenesis and UBE2O biology." (PMID 28673317, 2017). "UBE2O also significantly extended survival time of myeloma-bearing mice." (PMID 28673317, 2017). "Lentiviral infections were applied for UBE2O function in multiple myeloma (MM) cells." (PMID 28673317, 2017). "Myeloma xenografts with human MM cell line LP1 were established in immunodeficient nude mice, followed by intratumoral transfection of UBE2O plasmids delivered by in vivo jetPEI." (PMID 28673317, 2017). "DNA microarray revealed that UBE2O was expressed in normal bone marrow cells but downregulated in MGUS, smoldering MM and MM cells, which was confirmed by RT-PCR in primary MM cells, suggesting its potential role in myeloma pathophysiology." (PMID 28673317, 2017).
hepatocellular carcinoma (5 papers, 2021 to 2025). A malignant tumor that arises from hepatocytes. "Recent studies have also highlighted the potential of targeting the UBE2O/HADHA axis in the treatment of hepatocellular carcinoma (HCC), the most common primary malignant liver tumor and the sixth highest cause of cancer-related death." (PMID 39272922, 2024). "In summary, UBE2O reduces the effectiveness of interferon-α by degrading IFIT3 in hepatocellular carcinoma." (PMID 38129382, 2023). "UBE2O promotes hepatocellular carcinoma cell proliferation and invasion by regulating the AMPK/mTOR pathway." (PMID 36185617, 2022). "Ubiquitin Conjugating Enzyme E2O (UBE2O) has been found to be significantly correlated with the prognosis of hepatocellular carcinoma (HCC), and UBE2O is considered a potential therapeutic target in various types of cancer." (PMID 38129382, 2023). "The HPA database indicated that UBE2O exhibited protein expression patterns opposite those of IFIT3 in both liver tissue and hepatocellular carcinoma tissue, although its expression was positively correlated with that of BST2 and TRIM21." (PMID 38129382, 2023). "Nevertheless, the role of UBE2O in hepatocellular carcinoma (HCC) remains unknown yet." (PMID 34790050, 2021). "There was a negative correlation between UBE2O and IFIT3 protein expression in hepatocellular carcinoma patients." (PMID 38129382, 2023).
liver cancer (4 papers, 2021 to 2025). An epithelial or non-epithelial malignant neoplasm that arises from the liver. "ATO exerts anti-osteosarcoma effects by inhibiting UBE2O-mediated L3MBTL2 degradation, while arborinine blocks UBE2O’s degradation of substrates like AMPKα2 and demonstrates synergistic chemotherapeutic potential in breast and liver cancer models." (PMID 40426910, 2025).
head and neck squamous cell carcinoma (3 papers, 2022 to 2025). A squamous cell carcinoma that arises from any of the following anatomic sites: lip and oral cavity, nasal cavity, paranasal sinuses, pharynx, larynx, and salivary glands. "UBE2O promotes progression and EMT in head and neck squamous cell carcinoma." (PMID 36185617, 2022).
Alzheimer disease (2 papers, 2024 to 2025). A progressive, neurodegenerative disease characterized by loss of function and death of nerve cells in several areas of the brain leading to loss of cognitive function such as memory and language. "For example, age-associated reduction in UBE2O gene expression promotes neuronal death in Alzheimer’s disease." (PMID 39596581, 2024). "By targeting AβPP (amyloid-β precursor protein) for degradation, UBE2O potentially reduces amyloid-β plaque formation, suggesting a protective role in Alzheimer’s disease." (PMID 40426910, 2025). "Additionally, we will summarize recent advancements in understanding the role of UBE2O in various tumors, Alzheimer’s disease (AD), and metabolic diseases." (PMID 40426910, 2025). "There may therefore be a link between the variation in Ube2o expression and the fact that NMDA receptor activation is involved in Alzheimer’s disease." (PMID 39596581, 2024). "In addition to its role in tumorigenesis and cancer progression, UBE2O also plays significant roles in several non-tumor diseases such as Alzheimer’s disease (AD) and metabolic diseases." (PMID 40426910, 2025).
clear-cell renal cell carcinoma (2 papers, 2022 to 2025). "Clinical studies demonstrate that elevated UBE2O expression in clear-cell renal cell carcinoma (ccRCC) is strongly associated with adverse clinical outcomes." (PMID 40426910, 2025). "In conclusion, arborinine regulates the expression of UBE2O by inhibiting the activity of KDM1A, thereby inhibiting the proliferation, migration, and invasiveness of clear-cell renal cell carcinoma cells and reversing the EMT process." (PMID 40426910, 2025).
gastric cancer (2 papers, 2021). A primary or metastatic malignant neoplasm involving the stomach. "According to TCGA and GEO databases, UBE2O upregulation that is frequently detected in breast, bladder, liver, lung, esophageal, and head and neck cancer predicts poor clinical outcomes in breast, lung, and gastric cancer." (PMID 34790050, 2021).
metabolic syndrome (2 papers, 2024 to 2025). A cluster of metabolic risk factors for CARDIOVASCULAR DISEASES and TYPE 2 DIABETES MELLITUS. "The authors’ research indicates that UBE2O plays a significant role in obesity and metabolic syndrome." (PMID 40426910, 2025). "Through UBE2O knockout models, they managed to improve insulin sensitivity in diet-induced type 2 diabetes mice and demonstrated that UBE2O ablation protects mice against diet-induced obesity and metabolic syndrome." (PMID 39272922, 2024). "UBE2O could ameliorate obesity and metabolic syndrome by targeting AMPKα2 for degradation." (PMID 40426910, 2025).
Obesity (2 papers, 2024 to 2025). Accumulation of substantial excess body fat. "Hence, UBE2O is a critical regulator of the circadian clock, whose dysregulation is associated with many diseases, including cancer, diabetes, and obesity." (PMID 39272922, 2024).
pancreatic cancer (2 papers, 2023 to 2025). "In conclusion, UBE2O drives pancreatic cancer progression by driving the ubiquitin-dependent degradation of BIN1 and thereby activating c-Myc-driven oncogenic pathways." (PMID 40426910, 2025). "Functionally, UBE2O overexpression enhances pancreatic cancer cell proliferation, migration, and glycolytic activity in vitro, while UBE2O knockdown suppresses these phenotypes." (PMID 40426910, 2025). "CircPDK1 also serves as a skeleton to strengthen the contact of ubiquitin-conjugating enzyme E2O (UBE2O) with bridging integrator 1 (BIN1), causing UBE2O-mediated degradation of BIN1 and accelerating the advancement of pancreatic cancer." (PMID 37532687, 2023). "In pancreatic cancer, BIN1 protein levels are markedly downregulated and inversely correlated with UBE2O expression." (PMID 40426910, 2025).
anemia (1 paper, 2024). A reduction in the number of red blood cells, the amount of hemoglobin, and/or the volume of packed red blood cells. "Additionally, our data suggest that luspatercept, a drug approved for the treatment of anemia in MDS, acts through the upregulation of UBE2O, leading to a stimulation of effective erythropoiesis." (PMID 39272922, 2024).
B cell lymphoma (1 paper, 2022). "Ube2o ablation in two mouse models of lymphoma (an Em-Myc mouse model of B cell lymphoma and a Pten-deficient mouse developing T cell lymphoma) in which AMPKa2 is undetectable, did not produce a markedly antitumor effect, suggesting that AMPKa1 might not play a role in UBE2O-dependent tumorigenesis." (PMID 37533513, 2022).
breast tumours (1 paper, 2019). "Using immunohistochemistry of human breast tumours, there was a negative correlation between expression of UBE2O and AMPK-α2, but a positive correlation between UBE2O expression and S6 phosphorylation, a marker for the mTORC1 pathway." (PMID 31288625, 2019).
cervical cancer (1 paper, 2022). A primary or metastatic malignant neoplasm involving the cervix. "Thus, activating UBE2O might be a potential therapy for HeLa cell-associated cervical cancer." (PMID 36443833, 2022).
diabetes (1 paper, 2024). "This evidence suggests that the development of drugs interfering with UBE2O-AMPK interaction or the pharmacological inhibition of UBE2O activity could represent a powerful strategy for contributing to muscle insulin sensitivity, ameliorating diabetes and metabolic health." (PMID 39272922, 2024).
glioma (1 paper, 2022). A benign or malignant brain and spinal cord tumor that arises from glial cells (astrocytes, oligodendrocytes, ependymal cells). "Interestingly, our results showed that UBE2O dramatically reduced the secretion of exosome-related PTRF, suggesting that an increase of UBE2O expression might be an approach to treat glioma and ccRCC." (PMID 36443833, 2022).
Hepatic steatosis (1 paper, 2025). Steatosis is a term used to denote lipid accumulation within hepatocytes. "The whole-body or skeletal muscle-specific knockout of UBE2O improves the metabolic status of obese mice, enhances insulin sensitivity, reduces fat accumulation, and protects against hepatic steatosis." (PMID 40426910, 2025). "The results show that Ube2o–/– mice gained less body weight, had reduced fat mass and improved plasma lipid levels, and were significantly protected against hepatic steatosis when fed an HFD." (PMID 40426910, 2025).
hypochromic anemia (1 paper, 2024). Anemia caused by the reduction of hemoglobin in relation to the red cell volume. "Taking advantage of the UBE2O-null mouse model, they demonstrated that UBE2O deficiency is associated with a defective mechanism of protein ubiquitination, leading to the extensive intracellular accumulation of ribosomal proteins and the development of microcytic hypochromic anemia in mice." (PMID 39272922, 2024).
iron overload (1 paper, 2022). "Whole exome sequencing of 9 cases with unexplained primary iron overload identified 42 missense variants in 40 genes associated with iron metabolism pathway genes such as UBE2O p.K689R and PCSK7 p.R711W." (PMID 35668470, 2022). "We found recurrent p.K689R variant in UBE2O and a high frequency of mutations in PCSK7 in primary iron overload patients." (PMID 35668470, 2022). "In the present study, we firstly identified novel mutations by NGWES in a small number of patients with unexplained primary iron overload, then we screened for the mutations in the representative newly identified genes, UBE2O and PCSK7, in a larger cohort of primary iron overload patients." (PMID 35668470, 2022).
lung adenocarcinoma (1 paper, 2021). A carcinoma that arises from the lung and is characterized by the presence of malignant glandular epithelial cells. "We found that UBE2O is highly expressed in lung adenocarcinoma tissues than that in adjacent tissues." (PMID 32901121, 2021). "Importantly, we analyzed the association between UBE2O and Mxi1 expression in the paired lung adenocarcinoma tissues and found that there was a negative correlation between UBE2O and Mxi1 protein levels (P < 0.001)." (PMID 32901121, 2021).